CDRT4 (CMT1A duplicated region transcript 4)
Synonyms: FLJ36674
Tractability: No criterion of Open Targets' tractability assessment is met for any kind of drug.
Gene: Protein-coding gene on chromosome 17 (15,436,015 to 15,475,733, reverse strand). Ensembl gene ENSG00000239704.
Subcellular location (Human Protein Atlas): Mitochondria
Gene Ontology:
Molecular function: protein binding
Genetic constraint (gnomAD): Loss-of-function variants: 1 observed, 3.58 expected, observed/expected ratio (o/e) 0.28, 90% interval 0.098 to 1.29. That is too few expected variants to judge how well the gene tolerates losing a copy. Missense variants: 167 observed, 203.89 expected, observed/expected ratio (o/e) 0.82, 90% interval 0.72 to 0.93. Synonymous variants: 64 observed, 73.64 expected, observed/expected ratio (o/e) 0.87, 90% interval 0.71 to 1.07.
Homologues: Orthologues: chimpanzee CDRT4 (99% identical), dog CDRT4 (67% identical), mouse Cdrt4 (45% identical), rat Cdrt4 (45% identical).
Diseases named in the same sentence as CDRT4 in open-access papers:
CDRT4 is named in the same sentence as 3 diseases in open-access papers, as found by Europe PMC text mining. Sharing a sentence is not in itself a finding about the gene and the disease.
CDRT4 shares sentences with these, for which no sentence is quoted: breast carcinoma (1 paper); infection (1); pancreatic cancer (1).